GDF15 (growth differentiation factor 15)
Diseases named in the same sentence as GDF15 in open-access papers (continued):
Sharing a sentence is not in itself a finding about the gene and the disease.
Obesity (continued). "Furthermore, systemic overexpression of GDF15 was shown to prevent obesity and insulin resistance by increasing the expression of the main thermogenic and lipolytic genes and oxidative metabolism in BAT and WAT." (PMID 32265845, 2020). "Indeed, similar to its role in cancer-induced anorexia, GDF-15 also has an anorectic effect in obesity models." (PMID 33302552, 2020). "In obesity and diabetes mellitus, GDF15 upregulation has been described as well." (PMID 33003626, 2020). "Besides shifting the balance between obesity and leanness, GDF-15 also acts on immune cells in adipose tissue." (PMID 32508832, 2020). "Similar to Gdf15-deficient mice, mice lacking Gfral are prone to develop more severe obesity and IR." (PMID 33302552, 2020). "Moreover, in individuals with obesity or diabetes, circulating levels of GDF15 are higher than in unaffected individuals, and are positively correlated with serum glucose, HbA1c, and insulin resistance." (PMID 33003626, 2020). "Interestingly, the elevation of circulating GDF15 observed with metformin treatment in both studies was much more modest in chow-fed than HFD-fed mice, suggesting that obesity somehow potentiates GDF15 induction in response to metformin." (PMID 32310257, 2020). "For unknown reasons, the degree of obesity of our GDF15-/- line became milder as the generation number became higher." (PMID 32492819, 2020). "Furthermore, moderately elevated levels of GDF-15 (usually below 2 ng/ml) can be found in obesity, aging, autoimmune comorbidities or cardiovascular disease." (PMID 33123167, 2020). "More importantly, although obese and non- obese patients had similar outcomes, GDF15 was able to identify patients at risk of worse outcomes over time with higher GDF15 showing a worse survival 24 months post-surgery independent of obesity." (PMID 32671100, 2020). "However, GDF-15 shows a positive correlation with obesity progression and the development of complications such as T2D." (PMID 33302552, 2020). "GDF-15 has thus become an attractive target for reducing obesity." (PMID 33312159, 2020). "The lack of association between GDF15 and TG or blood sugar suggests they are unrelated to circulating GDF15 levels in obesity." (PMID 32671100, 2020). "Taken together, our findings suggest for the first time that GDF15 could not only be an important biomarker in cardiovascular disease but may also help determine the impact of obesity on cardiovascular outcomes." (PMID 32671100, 2020). "In this cross-sectional study, GDF-15 was measured in plasma and urine from 53 children with a renal transplant and 83 children with CKD and related to cardiovascular risk factors (hypertension, obesity, and cholesterol) and kidney function." (PMID 32089755, 2020). "These new findings provide new molecular insights about how diet and lipid metabolism may regulate the development of obesity and T2D, but also suggest that GDF-15 may be a marker of the metabolic activation of macrophages during obesity." (PMID 33302552, 2020). "Additionally, obesity had a significant effect on GDF15 levels, with higher levels observed in obese rats compared to their lean counterparts." (PMID 32374790, 2020). "Therefore, new noninvasive drugs to treat obesity are in high demand, and GDF15 appears as an attractive therapeutic option." (PMID 32911810, 2020). "Tissue macrophage infiltration is also observed in most pathological conditions such as obesity, T2D and cancer, indicating that macrophages may represent an important source of GDF-15 in these disorders." (PMID 33302552, 2020). "The observed rise in GDF15 concentrations in response to critical illness was also much larger than the increase that was previously reported for other pathological conditions such as obesity, and severity of illness appeared to be an important determinant." (PMID 32928255, 2020).
Obesity (continued). "Interestingly, GDF-15 production is also induced by metformin and, at least in mice, GDF-15 is responsible for the anti-obesity effects of this most commonly prescribed type 2 diabetes drug." (PMID 32508832, 2020). "However, it was the identification of GFRAL, a transmembrane receptor localised to the hindbrain, as the putative target for GDF15 and mediator of its weight lowering effects in rodents that framed GDF15 as a potential anti-obesity therapy." (PMID 31801546, 2019). "In individuals with obesity or diabetes, circulating levels of GDF-15 are higher than in unaffected individuals, and are positively correlated with blood concentrations of glucose, HbA1c, insulin resistance, C-reactive protein (CRP) and other cardiovascular risk factors." (PMID 30350239, 2019). "In this regard, GFRAL may act as both an upstream and downstream therapeutic target, with appetite suppression reducing both obesity and correlated visfatin levels, and GDF15 inhibition reducing downstream visfatin mediated pAKT." (PMID 31861872, 2019). "If GDF15 is playing a role in restraining progressive weight gain, this suggests that it might have a role in the therapy of obesity." (PMID 30639358, 2019). "Compared to wildtype animals, GDF15 knockout mice were more prone to high fat diet-induced obesity." (PMID 30070999, 2018). "GDF15 limits food uptake and obesity in experimental models." (PMID 30533221, 2018). "The UPRmt induced by skeletal muscle-specific OxPhos deficiency is also associated with enhanced lipolysis and fatty acid oxidation by the induction of growth differentiation factor 15 (GDF15), thereby protecting against the adverse effects of high-fat diet-induced obesity in mice." (PMID 30307158, 2018). "GDF15 is a transforming growth factor- β (TGF-β) superfamily member that has recently generated broad interest as a new target to develop pharmacotherapies for obesity and related comorbidities." (PMID 30070999, 2018). "Paradoxically, circulating GDF15 levels are increased in obesity." (PMID 30070999, 2018). "(i) GDF15 is strongly expressed in the liver compared to adipose tissue in obesity." (PMID 30533221, 2018). "Our data suggests that endogenous GDF15 has a protective role in obesity development and lack of GDF15 aggravates the progression of obesity and associated pathological conditions." (PMID 30070999, 2018). "Although NAFLD/NASH has been reported to be frequently associated with obesity or insulin resistance, to the best of our knowledge, the functional importance of GDF15 in NASH and related metabolic disorders has not been evaluated." (PMID 29717162, 2018). "Hence, our findings suggest that it would be worthwhile to test the ability of GDF15 to improve systemic metabolic homeostasis and decrease obesity in patients." (PMID 29674655, 2018). "Additionally, high GDF-15 tertile participants had greater smoking histories, more frequently had diabetes, hypertension, hyperlipidemia and obesity, and were more frequently classified at intermediate or high risk by HEART score." (PMID 28245821, 2017). "In addition, several studies implicate GDF-15 in aspects of metabolic disorders e.g. insulin resistance and obesity." (PMID 25590623, 2015). "Interestingly, people with anorexia nervosa or obesity also exhibit elevated circulating MIC-1/GDF15 levels, and obese people with type 2 diabetes exhibit still further elevations in MIC-1/GDF15 compared to non-diabetic obese patients." (PMID 22514681, 2012). "Because of the increase in GDF‐15 levels in atherosclerotic vessels of apoE−/− mice after CED, we investigated whether GDF‐15 affects obesity and blood lipid concentration using GDF‐15−/−/apoE−/− male mice generated from heterozygous matings." (PMID 23316317, 2012).
Obesity (continued). "The aim of this review is to synthesize recent evidence on the relationship between GDF-15 and different subclinical atherosclerosis markers, and to evaluate whether GDF-15 may represent an integrative biomarker reflecting shared pathways between atherosclerosis, obesity, and heart failure." (PMID 41597417, 2026). "The interactions between GDF15 and lipid metabolism suggest that it may hold therapeutic potential for obesity and relevant metabolic diseases, although further investigations are needed to clarify its precise mechanisms and long-term effects (and side effects)." (PMID 40837873, 2025). "In addition to obesity, other endocrinopathies reportedly impact GDF15 levels." (PMID 40019842, 2025). "In the future, based on its extensive pathophysiological mechanism, GDF-15 also carries potential for therapeutic applications, and studies are currently ongoing on its effectiveness against cardiometabolic disease, non-alcoholic fatty liver disease, and obesity." (PMID 41180477, 2025). "The hormone’s clinical relevance stems from its paradoxical roles: conditions of nutritional excess (e.g., obesity and diabetes mellitus), and up-regulated GDF15 expression may serve as a compensatory cytoprotective mechanism, maintaining homeostasis through negative energy regulation." (PMID 40837873, 2025). "Consequently, GDF-15 is considered a valuable biomarker for both obesity and T2DM." (PMID 41019919, 2025). "In addition, diabetes‐related complications, such as atherosclerosis development, as well as the presence of obesity itself may have influenced GDF15 levels." (PMID 38965822, 2024). "To investigate the contribution of GDF15 to the anti-obesity effect of artesunate, we used an adeno-associated virus (AAV8) expressing Gdf15-specific shRNA (shGDF15) to knock down GDF15 in the liver and kidney, from which artesunate-induced GDF15 is mainly derived." (PMID 38310105, 2024). "On the other hand, in chronic inflammatory states, such as atherosclerosis, obesity, steatohepatitis, and liver fibrosis, GDF15 signaling can either aggravate inflammation, e.g., in atherosclerosis, or ameliorate inflammation, such as in obesity, steatohepatitis, and liver fibrosis." (PMID 39643709, 2024). "In addition, physiological conditions like exercise induce GDF-15 could have a protective role against obesity and insulin resistance and also eliminate its reinforced stress markers like Atf3, Atf6, and Xbp1s in skeletal muscle after exercise." (PMID 38409184, 2024). "GDF-15 shows great promise to be a biomarker for disease prediction and prognosis, identifying at-risk groups who may benefit from intensive intervention and the potential application of GDF-15-based therapies in cancer cachexia, DM, and obesity." (PMID 37152099, 2023). "Furthermore, we discovered that decreasing levels of circulating FGF-21 and GDF-15 were associated with greater weight loss at one year regardless of the type of anti-obesity therapies." (PMID 37436597, 2023). "In addition, GDF-15 knockout mice on high-fat diets were more prone to obesity." (PMID 37152921, 2023). "Interestingly, GDF15 concentrations also positively correlate with obesity." (PMID 36992609, 2023). "Our findings ask whether or not GDF-15 is a key mediator of weight loss after anti-obesity treatments, particularly bariatric/metabolic surgery." (PMID 37436597, 2023). "So far, there are no studies investigating whether plasma GDF15 concentrations in youth with obesity are associated with NAFLD." (PMID 35194014, 2022). "Since these patients exhibited a significantly higher mean BMI than those participating in the conservative dietary program, this finding indicates that the correlation of GDF15 with T2D might be BMI-dependent and predominantly exists in individuals with advanced obesity." (PMID 36430499, 2022).
Obesity (continued). "GDF15 is a stress-inducing hormone and is released by cells, such as vascular smooth muscle cells, heart and endothelial cells, macrophages, and fat cells in response to external stimuli resulting from various stress states, such as obesity, insulin resistance, heart failure, and cancer." (PMID 36387916, 2022). "In patients with severe obesity, GDF15 expression is mostly restricted to the liver instead of AT and is reduced after bariatric surgery, suggesting that the liver could be a major source of GDF15 in obesity." (PMID 35909571, 2022). "Taking into account these biases, our genetic analyses did not support a causal association between normal human GDF15 plasma levels and obesity and diabetes, albeit a nominal finding of a causal association of WHR may warrant further investigation." (PMID 35916366, 2022). "Thus, elevated GDF15 levels in patients with obesity are further increased by the presence of T2DM." (PMID 36444166, 2022). "Thus, the mechanism underlying the obesity-dependent effect of CPT is highly probably due to serum levels of GDF15, which is relatively low and not sufficient to suppress food intake and body weight in lean mice." (PMID 35202387, 2022). "Moreover, macrophage TFEB protected against HFD-induced obesity by inducing growth differentiation factor 15 (GDF15), suggesting that the activation of the TFEB–GDF15 axis could play a crucial role in regulating obesity-induced metabolic diseases." (PMID 36231114, 2022). "GDF-15 levels are increased in human obesity, diabetes, and genetic lipodystrophy but also in patients with anorexia nervosa or after feeding restriction, and current views postulate a role for GDF15 in connecting somatic distress signals to the central control of energy balance." (PMID 35160008, 2022). "As a member of the transforming growth factor (TGF)-β subfamily, growth differentiation factor 15 (GDF-15) is a stress-responsive cytokine associated with various diseases such as cancers, cardiovascular disorders, mitochondrial disorders, hyperthyroidism, obesity and type 2 diabetes." (PMID 34638326, 2021). "However, whether dysregulation of FGF21 and GDF15 in obesity affects tolerance during IAV or SARS-CoV-2 infection remains to be experimentally confirmed." (PMID 34777390, 2021). "The existence, the functional role and clinical relevance of GDF15 and its signaling through a GFRAL/RET-dependent complex in gastric cancer (GC) and other human tumors remain to be elucidated, despite the widespread recognition of obesity as an important cancer-predisposing factor." (PMID 34149933, 2021). "While this did not translate to changes in circulating GDF15, it does suggest that alterations in adipose tissue phenotype could alter GDF15 expression in the absence of obesity associated adipose tissue dysfunction." (PMID 32310257, 2020). "By contrast, reconstitution of macrophage-depleted mice with Gdf15-deficient macrophages increases body weight and IR compared to mice reconstituted with Gdf15-proficient macrophages, showing that GDF-15 production by macrophages participates in obesity and T2D." (PMID 33302552, 2020). "Some support for the notion that chronic elevation of GDF15 action might be safe and effective in obesity is provided by studies demonstrating the chronic elevation of GDF15 by metformin and the importance of this action for metformin’s beneficial effects on weight." (PMID 32310257, 2020). "Moreover, CpGs in the VMP1/MIR21 locus are also among the top hits in several previous EWAS, including chronic inflammation marker C-reactive protein (CRP), cardiovascular biomarker GDF-15, obesity, childhood-onset Crohn’s disease, and inflammatory bowel disease." (PMID 30867049, 2019).
Obesity (continued). "The robust phenotype observed in the male mice suggests that endogenous GDF15 is important to protection against obesity development in obesogenic environment, and we propose that elevated GDF15 levels in obesity may have resulted from a response to overcome GDF15 resistance." (PMID 30070999, 2018). "Elevated GDF15 levels in obesity may have resulted from a response to overcome GDF15 resistance." (PMID 30070999, 2018). "However, the regulation of GDF15 expression in obesity and NAFLD is incompletely understood." (PMID 30533221, 2018). "However, the regulation of GDF15 in obesity-related human disease processes is poorly understood." (PMID 30533221, 2018). "Finally, to determine whether GDF15 affects systemic glucose tolerance and macrophage infiltration in a rodent model of obesity, we treated ob/ob mice (in which M1-like macrophages predominate in adipose tissue) with rGDF15." (PMID 29674655, 2018). "However, it is unclear why the circulating GDF15 levels increase in obesity and whether endogenous GDF15 is involved in obesity development." (PMID 30070999, 2018). "Due to some similarities in metabolic actions of thyroid hormone and GDF15, especially in preventing obesity and increasing thermogenesis, we therefore tested the hypothesis that thyroid hormone might increase circulating GDF15 levels in humans and further confirmed this regulatory axis in mice." (PMID 30687235, 2018). "GDF15 and FGF21 have received significant attention over the past decade for their potential as pharmacological agents to treat obesity and type 2 diabetes." (PMID 40787810, 2025). "In this sense, the important relationship of growth differentiation factor 15 (GDF15) and fibroblast growth factor 21 (FGF21) with metabolic regulation has exponentially increased the study of both proteins in relation to obesity and its comorbidities." (PMID 40377893, 2025). "Therefore, pharmacological approaches aimed at modulating GDF15 levels or its signaling pathway could provide new treatment strategies against conditions with dysregulated sympathetic activity including obesity, hypertension or idiopathic orthostatic hypotension." (PMID 41034527, 2025). "Hepatocyte-specific overexpression of GDF15 in high-fat diet (HFD)-fed mice resulted in high circulating GDF15 levels, which improved obesity and hepatic steatosis." (PMID 40260391, 2025). "GDF15 and FGF21 are stress‐responsive cytokines whose levels are increased in several diseases, including obesity and T2D, being most of them age‐related disorders." (PMID 40377893, 2025). "Growth differentiation factor 15 (GDF15), a member of the transforming growth factor superfamily, has been extensively researched in terms of its relationship with obesity, cachexia, and vascular diseases." (PMID 40234099, 2025). "Since their plasma levels increase with obesity, it has been proposed that GDF15 and FGF21 jointly impose a cap on weight gain during diet‐induced obesity." (PMID 40787810, 2025). "Glucuronyl C5-epimerase interacts with mature NAG-1/GDF15 to prevent its degradation and thereby exerts increasing anti-obesity effects." (PMID 40316530, 2025). "The circulating concentrations of GDF15 and FGF21 were significantly increased with obesity and further increased with IGT and T2D." (PMID 40828431, 2025). "This study aimed to analyse the relationship between changes in plasma GDF15 and FGF21 levels and the resolution of T2D or obesity improvements after bariatric surgery." (PMID 40377893, 2025). "Importantly, the interaction of GDF15 with its receptor GFRAL (glial cell derived neurotrophic factor receptor alpha-like) in the central nervous system is able to cause weight loss in diet-induced obesity and in other animal models of obesity via reduction of food and fat5 intake." (PMID 40820083, 2025). "Currently, several drugs targeting the GDF15/GFRAL axis are in clinical development for various indications, including obesity, heart failure, and cachexia." (PMID 40837873, 2025).